TPX2 (TPX2 microtubule nucleation factor)
Diseases named in the same sentence as TPX2 in open-access papers (continued):
Sharing a sentence is not in itself a finding about the gene and the disease.
cancer (continued). "The results support the potential of TPX2 in the treatment of castration-resistant tumors and highlight the induction of apoptosis due to AIM1 and TMED3 inhibition especially in the androgen independent cancer cells." (PMID 22761906, 2012). "In addition, studies have confirmed that the positively correlated co-expression genes NUSAP1, ASF1B, TPX2, and SKA1 are invariably involved in immune cell infiltration in numerous cancers, and thus contribute to the regulation of the tumor immune microenvironment." (PMID 38173030, 2024). "Similarly, TPX2 expression and M0 macrophage levels were positively correlated in 19 cancer types, while a negative correlation in THYM." (PMID 38315450, 2024). "In addition, AMG900 treatment in cancer cells suppresses most of the genes in the TPX2/AURKB subnetwork but not in the COL1A2 subnetwork." (PMID 35332150, 2022). "Whether the doughnut-shaped nuclei and unsealed nuclear envelopes are present in TPX2-overexpressing cancers and constitute non-canonical routes to genome rearrangements leading to transformation is worthy of further investigation." (PMID 32041138, 2020). "A recent study showed that aurora A kinase and the targeting protein for Xklp2 (TPX2) are novel co-regulators of the MYC pathway, suggesting that targeting of the aurora A kinase/TPX2 axis could be a therapeutic approach for MYC-driven cancers." (PMID 28036279, 2017). "Additionally, TPX2 and TTC26 expression inversely correlated with DNA methylation levels, suggesting that CNV alterations and epigenetic modulation may synergistically drive their dysregulation in cancer." (PMID 40599775, 2025). "However, TPX2’s impact on anoikis in malignant tumors has not been reported." (PMID 40599775, 2025). "Since Aurora-A is upregulated in certain cancer cell lines, which could influence the stoichiometry and function of the kinase:co-activator complexes, expression levels of these factors (i.e. Aurora-A, CEP192, TPX2, TACC3 and BORA) were determined across cell lines (Fig. EV1A)." (PMID 39327527, 2024). "In addition, TPX2 may have a role in the maintenance, rather than the establishment, of chromosomal instability in cancer cells, by fuelling mitotic errors through impairing correct spindle assembly." (PMID 32041138, 2020). "To date, however, there is no report, demonstrating an interaction between TPX2 and IGFBP-3 in any cancer cells." (PMID 25914189, 2015). "In our study, there was a negative correlation between TPX2 and MHC genes in most cancers." (PMID 38315450, 2024).
tumor (153 papers, 2004 to 2026). "Eventually, with regard to PFI, in 11 tumor types, high TPX2 levels were associated with poor prognosis." (PMID 38315450, 2024). "Higher TPX2 expression was associated with worse OS in 10 tumor types, while in THYM, TPX2 up-regulation was related to improved OS." (PMID 38315450, 2024). "The association between TPX2 expression and the infiltration abundance of the six main immune cell types in the tumor microenvironment of HCC was explored using TIMER 2.0." (PMID 38833082, 2024). "TPX2 expression and its association with prognosis, immune infiltration, tumor mutations, and signaling pathways in HCC were analyzed using UALCAN, BoxKaplan-Meier Plotter, GEPIA, Human Protein Atlas, TIMER 2.0, and SangerBox." (PMID 38833082, 2024). "We investigated the correlation of TPX2 with tumor mutational burden (TMB), microsatellite instability (MSI) and neoantigens." (PMID 38315450, 2024). "Targeting protein for Xenopus kinesin-like protein 2 (TPX2) overexpression in human tumours is associated with increased malignancy." (PMID 37142730, 2023). "We detected high TPX2 expression in 13.7% of all tumour samples, which was significantly associated with shorter patient PFS (5.9 vs 2.0 months, P < 0.001, HR 2.74, 95% CI 1.63–4.61) and OS (9.3 vs 4.4 months, P < 0.001, HR 2.52, 95% CI 1.52–4.16)." (PMID 37142730, 2023). "According to a meta-analysis, increased expression of the targeting protein for Xenopus kinesin-like protein 2 (TPX2) is associated with poor OS in gastrointestinal-tract cancers, old age, and tumor T stage in GC." (PMID 37238607, 2023). "Survival curve indicated that higher expression level of TPX2 was significantly associated with sPRCC2 patients’ overall survival and it is also correlated with higher clinical stage, tumor T stage and N stage." (PMID 36927438, 2023). "Decreasing pattern of gene expression within the model associated with lower expression in the tumor and normal samples was found in genes such as TPX2 and SMC4." (PMID 37627150, 2023). "Yuan at al. confirmed that ASPM, FOXM1, RACGAP1, and TPX2 were significantly associated with not only tumor progression but also prognosis of ACC." (PMID 35693556, 2022). "We find that increased TPX2 nuclear expression is significantly associated with tumor grade, clinical stage, estrogen receptor (ER) status, progesterone receptor (PR) status, and both disease-specific and overall survival." (PMID 33622270, 2021). "In two NB patient groups belonging to all tumor stages, high TPX2 gene expression was associated with decreased relapse-free, and event-free survival rates." (PMID 31557970, 2019). "TNM stage, tumor grade, postoperative adjuvant therapy, TPX2 expression and MMP12 expression were all associated with OS (P < 0.05)." (PMID 30305064, 2018). "ROC curve indicated that CCNB2, FBXO5, KIF4A, MCM10, and TPX2 exhibited excellent diagnostic efficiency for normal and tumor tissues." (PMID 30254986, 2018). "Clinical sample analysis also indicates that TPX2 expression is associated with the tumor–node–metastasis stage, tumor numbers, and tumor differentiation in the HCC tissues." (PMID 30100882, 2018). "Immunohistochemical staining showed that TPX2 over-expression was significantly associated with advanced age (P = 0.001) and tumor T stage (P = 0.003)." (PMID 27777511, 2016). "A lower DPEP1 expression or a higher TPX2 expression in tumor was associated with poor survival in the Maryland validation cohort (P = 0.016 and P = 0.007 respectively, Kaplan-Meier log-rank test), consistent with our results in the Germany test cohort." (PMID 22363658, 2012). "TPX2 plays a critical role in various cellular and molecular processes resulting in growth and metastasis, mitotic survival, and is linked to the radiosensitivity of tumor cells." (PMID 41602310, 2026).
tumor (continued). "Our findings establish TPX2-centered networks together with biological pathways implicated in mitotic regulation and DNA damage repair as key drivers of tumor evolution, providing a biologically informed source for biomarker development, drug testing and mechanistic studies." (PMID 41402347, 2025). "Evidence suggests that targeting TPX2 in tumor cells could enhance genomic instability, and significant associations between TPX2 and the prognosis of tumors with genomic instability have been proposed." (PMID 38833082, 2024). "Cox regression analysis in DFI demonstrated that in 7 tumor types, TPX2 was a high-risk factor." (PMID 38315450, 2024). "Reportedly, TPX2 is abnormally expressed in malignancies, and due to the abnormal amplification of TPX2 centrosomes, it often leads to DNA heteroploidy and polyploidy formation, causing massive proliferation and deterioration of tumor cells and affecting the cell cycle and apoptosis." (PMID 38833082, 2024). "In 15 tumor types, high TPX2 expression was a risk factor, while in COAD, it was protective." (PMID 38315450, 2024). "Therefore, the findings obtained by numerous researchers in different fields agree that high TPX2 expression in tumor tissues increases the prognostic risk for patients and is detrimental to their survival, similarly to the findings of the present study." (PMID 38833082, 2024). "Further analysis revealed the potential association of TPX2 expression with tumor stage and grade." (PMID 38833082, 2024). "Furthermore, the association between TPX2 expression and these top 5 genes in all tumor types from the TCGA database was also illustrated in the heatmap." (PMID 38643462, 2024). "Ten types of tumors showed significant associations between TPX2 expression and tumor stage." (PMID 38315450, 2024). "Finally, the gene set enrichment analysis implicated TPX2 in the regulation of aminoacyl tRNA biosynthesis, which is the most important tumor cell cycle signaling pathway." (PMID 36304254, 2022). "Deficiency of TPX2 is able to hinder the epithelial-mesenchymal transition of tumor cells." (PMID 35395834, 2022). "Moreover, in hepatic cell cancer (HCC), expression of Ccnb1 and Tpx2 was positively associated with higher immune cell infiltration in tumours, suggesting potential immune-regulatory roles for the proteins." (PMID 36010935, 2022). "Regardless of whether TPX2 overexpression is caused by the underlying amplification, overexpression of TPX2 positively correlates with tumor grade, stage, lymph node metastasis, remote metastasis, recurrence, and a poor prognosis and poor patient survival." (PMID 30177840, 2019). "Importantly, overexpression of AURKA and TPX2 has been linked to tumor development at different levels." (PMID 27827897, 2016). "Additionally, it was found that the expression of TPX2 was associated with tumor grade, stage, lymph node metastasis, and tumor size pathological type." (PMID 27777511, 2016). "In addition, we also evaluated PFI and confirmed that in 15 tumor types, TPX2 was a high-risk gene." (PMID 38315450, 2024). "Polymorphisms in several other tumor cell autonomous metastasis susceptibility genes identified in our laboratory including Sipa1, Rrp1b, and Brd4 are prognostic only in ER+ patients, and stable expression of Brd4 can also differentially regulate the Tpx2 network." (PMID 22693453, 2012). "Taken together these results demonstrate a causal role for Arid4b in tumor growth and metastatic progression and suggest that mechanisms of action involve modification of epigenetic state via the mSIN3A complex and regulation of the conserved Tpx2 gene network." (PMID 22693453, 2012). "In vivo, TPX2 silencing in xenograft models reduced tumor growth and altered autophagy marker profiles." (PMID 42311261, 2026). "In vivo trials illustrated that CEP55 knockdown inhibited tumor growth and downregulated key proteins in the TPX2-AURKA-PI3K-AKT and ferroptosis resistance pathway." (PMID 41617029, 2026).
tumor (continued). "TPX2, CENPA and RRM2 showed the strongest association with elevated PSA levels, particularly in the > 4 ng/mL group, indicative of higher tumor burden and poorer prognosis." (PMID 41402347, 2025). "BCL9 and TPX2 are significantly upregulated proteins in tumor tissues compared to the normal adjacent tissues (NATs)." (PMID 40362354, 2025). "By analyzing LC-MS/MS data from the CPTAC cohort, we found that both BCL9 and TPX2 levels were significantly elevated in ccRCC tumor samples compared to paired normal adjacent tissues." (PMID 40362354, 2025). "To explore the potential mechanism by which TPX2 lactylation affects tumour progression, we first investigated the level of TPX2 lactylation during cell cycle using Hep3B cells synchronized in different cell cycle phases." (PMID 40107714, 2025). "Herein, our analysis identifies gene expression changes across H. pylori–associated disease progression, with hub genes like CXCL1 and TPX2 showing early bacterial effects and later tumor-driven changes." (PMID 40445003, 2025). "Then, tumours with high nuclear TPX2, revealed by immunohistochemical analysis, were analysed for aneuploidy features, assessed by FISH." (PMID 39195284, 2024). "We found that TPX2 correlated with tumor purity in HCC, and its high TPX2 expression was linked to worse cumulative survival in HCC in the TIMER 2.0 analysis." (PMID 38833082, 2024). "For tumor invasion status and lymph node metastasis status, a significant difference existed in the rate of strong positive TPX2 expression (both p < 0.001)." (PMID 38466034, 2024). "Genes such as BUB1, TPX2, and ESPL1 demonstrated significant associations with patient survival outcomes and tumor progression, suggesting their potential utility as prognostic biomarkers for risk stratification and treatment selection." (PMID 39596419, 2024). "In subgroups divided by tumor stage, expression of TPX2 tended to increase with tumor stage, with the highest TPX2 expression in stage 3 tumors and an obvious decrease in TPX2 expression in stage 4 tumors." (PMID 38833082, 2024). "The IHC data confirmed the enhanced level of TPX2 in HCC tumor tissues compared to that in the normal controls." (PMID 38833082, 2024). "Consistently, according to immunofluorescence images, the TPX2 protein was mostly distributed in nucleoplasm of RH-30 and U-2 OS tumor cells." (PMID 38315450, 2024). "Consistent with our findings, previous studies have shown enhanced TPX2 expression in most tumor tissues, which is detrimental to patient survival." (PMID 38833082, 2024). "This was consistent with results obtained from analyses for TPX2 only, that is, TPX2 showed strong positive correlations with pathways, including tumor proliferation signature, G2M checkpoints, DNA damage repair, and DNA replication." (PMID 38833082, 2024). "While for tumor tissue, the staining intensity was moderate, indicating an increased expression of TPX2 in tumor tissue." (PMID 38833082, 2024). "Further, we examined the relationship of TPX2 expression with clinical features, and the tumor microenvironment." (PMID 38315450, 2024). "The down-regulation of TPX2 expression in tumor-infiltrating CD8+ T lymphocytes in HCC leads to the inactivation of the NF-κB signaling pathway, resulting in a weakened anti-tumor effect of these lymphocytes." (PMID 38426090, 2024). "The AurkA/TPX2 complex is overexpressed in several tumour types (breast, lung, prostate, ovarian, and others) and contributes to aneuploidy as well as CIN, favouring tumour heterogeneity and drug resistance." (PMID 39195284, 2024). "In the tumor model in nude mice, the growth of transplanted tumors in the sh‐TPX2 group was significantly inhibited compared with that in the sh‐Ctrl group." (PMID 38466034, 2024). "TPX2 accelerated tumor growth via suppressing apoptosis and ROS production in OC cells by modulating Lamin A/C's stability." (PMID 36789877, 2023).
tumor (continued). "We next investigated publicly available databases to assess the RNA expression of transcripts encoding for KIF11, KIF15, TPX2, and AURKA in EWS patient tumor samples using BioGPS (E-GEOD-12102)." (PMID 37894278, 2023). "Depletion of TPX2 significantly inhibited cell viability and migration in vitro as well as tumor growth in vivo." (PMID 37770979, 2023). "Of note, the results revealed that BIRC5, BUB1, and TPX2 were positively correlated with tumor purity, whereas GNG7 and SST were negatively correlated with tumor purity." (PMID 36863706, 2023). "The prognostic impact of TPX2 expression was examined in the tumour tissue of 139 patients with advanced PDAC (aPDAC) treated within the AIO-PK0104 trial or translational trials and of 400 resected PDAC (rPDAC) patients." (PMID 37142730, 2023). "Tumor sizes were less in the TPX2 KD group compared to those in the control group, suggesting that TPX2 can accelerate tumorigenesis of OC cells." (PMID 36789877, 2023). "Tumours showing high TPX2 expression levels displayed high gemcitabine-resistance scores, as high TPX2 expression co-segregated with the expression of genes known to be associated with gemcitabine resistance." (PMID 37142730, 2023). "It should be noted that miR-330-3p and TPX2 are merely two components of a complex regulatory network, and their specific roles and effects on tumor growth are contingent upon various factors in the experimental context." (PMID 37342327, 2023). "We also analyzed the correlation between TPX2 expression levels and the tumor microenvironment and immune cell infiltration." (PMID 36304254, 2022). "Several mitosis-associated genes, including AURKA, DLGAP5, TPX2, KIF11, and CKAP5, were overexpressed in tumor tissues, and associated with cell proliferation and poor OS." (PMID 36499051, 2022). "A bone marrow transfer experiment with TPX2-knockdown or TPX2-overexpressing cells into tumor-bearing CD8−/− mice showed that tumor growth was significantly delayed by TPX2-overexpressing CD8+ T cells but enhanced by TPX2-knockdown CD8+ T cells." (PMID 35273149, 2022). "Compared to mice that received control CD8+ T cells, mice that received Tpx2-overexpressing CD8+ T cells showed obviously limited tumor growth, while those that received Tpx2-depleted CD8+ T cells showed enhanced tumor growth." (PMID 35273149, 2022). "TPX2 can stimulate the proliferation, invasion and metastasis of tumor cells through the AKT pathway." (PMID 35774141, 2022). "Taken together, our data supported the notion that HDAC1 inhibitor retards the initiation and development of CC via mediating the TPX2/Snail axis, highlighting the anti-tumor molecular network functioned in CC." (PMID 35395834, 2022). "When we stratified the HCC tissues into TPX2high and TPX2low groups according to the expression of TPX2 in tumor-infiltrating lymphocytes (TILs), we found a greater proportion of exhausted immune cells (PD-1+TIM-3+) in TPX2low HCC tissues." (PMID 35273149, 2022). "Meanwhile, TPX2 overexpression diminished the inhibitory effect of HDAC1 silencing on tumor volume and weight of nude mice." (PMID 35395834, 2022). "Based on the GEO datasets, TPX2 shows a higher mRNA level in the HBV-HCC tissues than that in non-tumor groups (p<0.001)." (PMID 36204642, 2022). "The results showed that the expression of ACACB, ATP8B4, C14orf28, CIRBP, and DTWD1 were higher in normal tissues, and the content of CDC6, DSP, HMGB3, HNRNPA3P1, PPP1R14C, and TPX2 were higher in tumor tissues." (PMID 35778922, 2022). "According to the expression levels of TPX2 in tumor-infiltrating immune cells, the 20 HCC samples were divided into two groups: TPX2high and TPX2low." (PMID 35273149, 2022). "We found that CD8+ T cells overexpressing TPX2 dramatically limited tumor growth, and anti-PD-1 therapy synergistically restricted tumor growth." (PMID 35273149, 2022). "Apart from TPX2, we also tested the effect of other covariates, such as age, tumor grade, FIGO stage, and histological type." (PMID 35356748, 2022).